HIF1A (hypoxia inducible factor 1 subunit alpha)
Diseases named in the same sentence as HIF1A in open-access papers (continued):
Sharing a sentence is not in itself a finding about the gene and the disease.
cardiomyopathy (21 papers, 2010 to 2025). A disease of the heart muscle or myocardium proper. "MIF and HIF-1α expression levels in myocardial samples showed a close correlation (R2 = 0.6971, p < 0.0001, n = 30) hinting at an association with hypoxia-induced HIF-1α expression with consecutive MIF gene regulation in cardiomyopathy." (PMID 29027966, 2017). "HIF-2α, a paralog of HIF-1α, is the critical effector in obesity-associated cardiomyopathy." (PMID 30158902, 2018). "MIF and HIF-1α expression depends on the underlying type of cardiomyopathy." (PMID 29027966, 2017). "In previous studies, our group found that certain drugs reduce the lipotoxicity of cardiomyocytes through mTOR/HIF-1α dilution and can also resist cardiomyopathy through ROS/p38/JNK coupling." (PMID 39273228, 2024). "Consistently, Hif1α-KO mice also exhibited significant resistance to ISO-induced TTS-like cardiomyopathy, showing reduced plasma cTnT levels and preserved LVEF." (PMID 35132957, 2022). "As such, we used Lyz2-Cre–driven myeloid Hif1α–deficient mice (Hif1α-KO) as a myeloid loss-of-function model and studied ISO-induced TTS-like cardiomyopathy." (PMID 35132957, 2022). "Constitutive cardiac-specific over-expression of Hif1a leads to changes in cellular metabolism and increased glucose utilization, resulting in cardiomyopathy in aging mice." (PMID 30158902, 2018). "Furthermore, the decreased expression level of Hif1α in chemotherapy‐induced cardiomyopathy has been identified in the RNA‐seq data from GSE172181, GSE37260, and GSE157282." (PMID 40411250, 2025). "Furthermore, long-term constitutive overexpression of HIF-1α results in increased glucose uptake and the development of cardiomyopathy." (PMID 27422990, 2016). "However, the constitutive expression of HIF-1α and chronic long-term activation of HIF-1α pathways over time induce cardiomyopathy in transgenic mice with HIF-1α cardiac-specific overexpression." (PMID 24502509, 2014). "In cardiomyopathy, it has been reported that circ-Foxo3 interacts with anti-senescent proteins ID-1 and E2F1, as well as anti-stress proteins FAK and HIF1α, leading to the relocation of these proteins in cytoplasm." (PMID 38360615, 2024). "Meanwhile, circ-Foxo3 expression level is upregulated in aged patient and mice tissues, overexpression of circ-Foxo3 contributes to the progression of senescence in mice Dox-induced cardiomyopathy cells by interacting with ID1, E2F1, FAK, and HIF1A." (PMID 28219405, 2017). "On the other hand, a cardiac overexpression of Hif-1α under a non-pathological condition mediates beneficial effects on the heart on the short term, but chronic overexpression leads to cardiomyopathy in the aging mice." (PMID 39820339, 2025). "The role of Hif-1α in the development of cardiomyopathies seems to be cell type specific and HIF isotype specific, because endothelium expressed Hif-1α seems to have a protective role in the development of cardiomyopathies." (PMID 39820339, 2025). "Although involvement of Hif-1α was not investigated mechanistically, this observation is in line with our finding that downregulation of Hif-1α is beneficial in cardiomyopathies." (PMID 39820339, 2025). "In contrast, shorter-term constitutive overexpression of HIF-1α mRNA in cardiomyocytes did not result in cardiomyopathy, but this construct only produced a barely detectable increase in HIF in normoxia." (PMID 27422990, 2016).
colorectal tumors (21 papers, 2009 to 2025). "MiR-1 had been associated with the Warburg effect in colorectal tumor cells, but the mechanisms by which miR-1 inhibited glycolysis with affecting HIF-1α expression needed exploration." (PMID 28471448, 2017). "In vivo studies related these genetic variations to many aggressive clinical features of cancer, such as the ulcerative growth pattern in colorectal tumors, suggesting that HIF-1α polymorphism is associated with cancer." (PMID 24260383, 2013). "Propranolol decreases HIF-1α accumulation as well as CA IX levels, thereby disadvantaging colorectal tumour cells in adaptation to hypoxia and acidosis." (PMID 33228233, 2020). "After normalization, we found an increased level of HIF1α in both analysed colorectal tumour cell lines after blockade by propranolol under hypoxia." (PMID 33228233, 2020). "In human colorectal tumors, HIF-1α expression positively correlated with genes shown to be regulated by HIF-1α in MC-38 tumors." (PMID 33142239, 2020). "Here we tested the role of HIF-1α in tumor cells on colorectal tumor development in an orthotopic mouse model using MC-38 mouse adenocarcinoma cells, where the stromal compartment has normal HIF-1α activity." (PMID 33142239, 2020). "In summary, we have found that HIF-1α activity increases in HCT116 colorectal tumor cells following exposure to intermittent hypoxia mimicking OSA." (PMID 30669593, 2019). "Peri-necrotic areas in human primary colorectal tumors and liver metastases showed strong HIF1α and CAIX staining, reflecting the hypoxic nature of this tissue." (PMID 29156796, 2017). "In contrast, increased tumor AA is associated with longer disease-free survival and decreased HIF-1α and HIF stimulated gene products in human colorectal tumors." (PMID 26547841, 2015). "We also found a significant increase in HIF1A protein levels 10' postsurgery of colorectal tumors which, however, declined again at later timepoints." (PMID 25526028, 2014). "HIF-1α also competes with T-cell factor-4 (TCF-4) to bind β-catenin and form a HIF-1α/β-catenin complex, accompanied by increased HIF-1α transcriptional activity in colorectal tumors." (PMID 25566498, 2014). "On the other hand, in colorectal tumors, metabolic reprogramming represents an important process during carcinogenesis and it has been described that glycolysis is associated with the overexpression of key factors that include the PI3K/Akt/HIF-1α pathway." (PMID 40072116, 2025). "Moreover, PRMT3 expression level of colorectal tumor tissues was positively correlated with HIF1α expression level of colorectal tumor tissues." (PMID 34753906, 2021). "Lastly, when DSS was given together with azoxymethane to induce tumorigenesis in the colon, we found that hMRP8 Hif-1a KO mice exhibited comparable levels of colorectal tumors to those of WT mice, indicating that HIF-1α in myeloid cells is dispensable for tumorigenesis." (PMID 29967068, 2018). "Interestingly, a subunit of HIF-1, HIF-1a, has been reported as being overexpressed in colorectal tumors and contributing to chemotherapeutic resistance." (PMID 19270743, 2009). "However, from TNM database it is evident that expression of HIF1α and VEGFA is significantly (p = 3.48e−04 and 1.23e−113) higher in colorectal tumor tissues compared to the normal tissues." (PMID 40045186, 2025). "Taken together, RhoB, HIF1A, Met, MAPK6, and PKM may play key roles in promoting colorectal tumor formation in males." (PMID 38347027, 2024).
colorectal tumors (continued). "However, the relationship between COX-2 and HIF-1α can be inferred from a previous study demonstrating that COX-2 can be transcriptionally up-regulated by HIF-1α under hypoxic conditions and that elevated COX-2 activity promotes the survival of colorectal tumor cells." (PMID 25249371, 2014).
depression (21 papers, 2019 to 2025). "We found that thalamic hemorrhagic stroke causes mechanical allodynia, anxiety- and depression-like behaviors, and peri-thalamic lesion site HIF-1α/NLRP3 signaling upregulation and glial cell activation." (PMID 36944982, 2023). "The findings of Vettori and colleagues cited above added to our understanding that such a mechanism can be associated with stabilization of HIF-1α by GCs which are chronically elevated in depression." (PMID 34360746, 2021). "The lactylation of HIF-1α and the neuroprotective protein membrane-organizing extension spike protein has been implicated in premature cellular senescence, contributing to the manifestation of depression and anxiety symptoms in individuals with PTSD." (PMID 40226593, 2025). "The collective findings not only establish an empirical foundation for using honokiol in the clinical management of depression but also propose the possibility of the HIF-1α-VEGF pathway as a viable therapeutic target for depression treatment." (PMID 38001538, 2023). "The neurocircuit mechanisms through which thalamic HIF-1α/NLRP3 inflammatory signaling causes CPSP-related anxiety and depression are unclear." (PMID 36944982, 2023). "Collectively, activation of the HIF-1α-VEGF signaling pathway is a promising strategy to improve depression-like behaviors." (PMID 36091747, 2022). "Among these core targets, SIRT1, HIF1A, ESR1, VEGFA, HSP90AA1 and PTGS2 are well documented to be associated with depression." (PMID 36496991, 2022). "In summary, the HIF-1α-VEGF signaling pathway is closely related to the treatment of depression, which is consistent with our experimental results." (PMID 36091747, 2022). "The results showed that all core targets had good docking activity with honokiol (binding energy < −5.0 kcal/mol), further confirming that honokiol can play a therapeutic role in depression by modulating the HIF-1α-VEGF pathway." (PMID 36091747, 2022). "We believe these findings collectively demonstrate that honokiol is a promising and effective drug for the treatment of depression, and HIF-1α-VEGF pathway is a promising target." (PMID 36091747, 2022). "In depression, hypocretin‐1 may impose an adverse regulatory effect on the hypoxia‐inducible factor‐1α (HIF‐1α) pathway through hypocretin receptor 1, thereby disrupting the glycolytic pathway and resulting in reduced lactate release from astrocytes." (PMID 39119889, 2024). "To confirm the involvement of HIF-1α and NLRP3 in CPSP and associated anxiety and depression, we knocked down thalamic HIF-1α and NLRP3 through microinjection of HIF-1α siRNA or NLRP3 siRNA into the VPL of thalamus 3 days before microinjection of collagenase into the same regions." (PMID 36944982, 2023). "This study demonstrated for the first time that SGB could improve CPSP with comorbid anxiety and depression by increasing cerebral blood flow and inhibiting HIF-1α/NLRP3 inflammatory signaling." (PMID 36944982, 2023). "HIF1A has been proposed to have a protective effect on depression." (PMID 36746927, 2023). "Thus, we determined the causal relationship between local neuroinflammation and CPSP-related anxiety and depression by inhibiting thalamic HIF-1α/NLRP3 inflammatory signaling." (PMID 36944982, 2023). "The aim of the present study was to investigate the necessity of the HIF-1α-VEGF pathway in enhancing neuronal synaptic plasticity with honokiol and to clarify the antidepressant effect of honokiol on CUMS depression rat models by activating the HIF-1α-VEGF pathway." (PMID 36091747, 2022). "Taken together, the results do not only provide an experimental basis for honokiol in the clinical treatment of depression but also suggest that the HIF-1α-VEGF pathway may be a potential target for the treatment of depression." (PMID 36091747, 2022).
depression (continued). "In a study using a CUMS model of depression, the TLR4/MyD88/NF-κB and HIF-1α-VEGF signaling pathways in the hippocampus underwent significant changes, contributing to neuroinflammation and depressive behaviors." (PMID 40149760, 2025). "SGB increases cerebral blood flow to suppress HIF-1α/NLRP3 inflammatory signaling, improving the CPSP and comorbid anxiety and depression." (PMID 36944982, 2023). "We found that HIF-1α/NLRP3 signaling was critical for the development of CPSP and its related anxiety and depression." (PMID 36944982, 2023). "We next inhibited HIF-1α and NLRP3 by intra-thalamic injection of YC-1 (HIF-1α inhibitor) and MCC950 (NLRP3 inhibitor) and assessed mechanical pain sensitivity and anxiety- and depression-like behaviors." (PMID 36944982, 2023). "All these results suggest that inhibiting HIF-1α and NLRP3 prevented CPSP-related anxiety and depression." (PMID 36944982, 2023). "The most striking finding of this study is that inhibiting thalamic HIF-1α/NLRP3 inflammatory signaling was effective to prevent the anxiety and depression related to CPSP." (PMID 36944982, 2023). "Genetic knockdown of thalamic HIF-1α and NLRP3 significantly attenuated mechanical allodynia and anxiety- and depression-like behaviors following thalamic hemorrhage." (PMID 36944982, 2023). "Inhibiting thalamic HIF-1α/NLRP3 signaling prevented thalamic hemorrhage stroke-induced CPSP, anxiety, depression, and peri-thalamic lesion site neuroinflammation." (PMID 36944982, 2023). "Our study showed that HIF-1α/NLRP3 inflammatory signaling contributed to the CPSP and comorbid anxiety and depression." (PMID 36944982, 2023). "Our data demonstrated that thalamic HIF-1α/NLRP3 inflammatory signaling was responsible for the comorbid anxiety and depression in CPSP rats." (PMID 36944982, 2023). "Upregulated HIF-1α/NLRP3 signaling in the peri-thalamic sites activated microglia and astrocytes, releasing pro-inflammatory cytokines and oxidative stress, leading to CPSP and comorbid anxiety and depression." (PMID 36944982, 2023). "However, pharmacological activation of thalamic HIF-1α and NLRP3 with specific agonists significantly eliminated the therapeutic effects of SGB on mechanical allodynia and anxiety- and depression-like behaviors following thalamic hemorrhage." (PMID 36944982, 2023). "SGB inhibited HIF-1α/NLRP3 inflammatory signaling and could treat CPSP and comorbid anxiety and depression." (PMID 36944982, 2023). "In addition to suppressing HIF-1α/NLRP3 inflammatory signaling, SGB significantly attenuated thalamic hemorrhage-induced CPSP and comorbid anxiety and depression." (PMID 36944982, 2023). "However, pharmacological activation of thalamic HIF-1α/NLRP3 signaling eliminated the therapeutic effect of SGB on CPSP with comorbid anxiety and depression." (PMID 36944982, 2023). "After silencing HIF‐1α with shRNA‐HIF‐1α, HIF‐1α could not be further expressed, and SAM could not further improve the depression‐like behavioral changes, nor did it have a significant effect on neuroinflammation and the activation of microglia." (PMID 40927974, 2025).
fibrosarcoma (21 papers, 2010 to 2023). A malignant mesenchymal fibroblastic neoplasm affecting the soft tissue and bone. "Using HT1080 fibrosarcoma flank tumor xenografts generated in athymic nude mice, we examined the levels of hypoxia and HIF-1α in control tumors and the tumors treated with DC101, an anti-VEGFR-2 antibody." (PMID 22684860, 2013). "Consequently, reduced CYP1A1 expression in mice with a myeloid HIF-1α knockout developed fewer tumors in the MCA-induced fibrosarcoma model." (PMID 30615637, 2019). "Shih identified that TGF-β1 stimulated the expression of HIF-1α and its downstream gene VEGF in fibrosarcomas." (PMID 25723475, 2015). "Recently, HIF-1α inhibition by CTM effectively reduced hypoxia-dependent transcription and sensitized hypoxic HT 1080 human fibrosarcoma cells in vitro to radiation." (PMID 21050481, 2010). "In a carcinogen 3-methylcholanthrene (MCA)-induced fibrosarcoma mice model, NOX4 was proved to regulate the tumour-vessel density through stabilization of HIF-1α and induction of VEGF expression, while a significant 38% reduction in tumour vascularization in fibrosarcomas of Nox4-/- mice." (PMID 34930338, 2021). "As little is known how myeloid HIF affects tumor development, we injected the polycyclic aromatic hydrocarbon (PAH) and procarcinogen 3-methylcholanthrene (MCA; 100 μg/100 μl) subcutaneously into myeloid-specific Hif-1α and Hif-2α knockout mice (C57BL/6J) to induce fibrosarcomas (n = 16)." (PMID 27015123, 2016).
obstructive sleep apnea (21 papers, 2012 to 2025). "The association of Hypoxia-Inducible Factor 1-alpha (HIF-1α) with the pathophysiological processes of obstructive sleep apnea (OSA) is a critical element." (PMID 38672697, 2024). "Clinical conditions such as obstructive sleep apnea—characterized by intermittent nocturnal hypoxemia—and chronic pulmonary diseases activate the hypoxia-inducible factor-1 alpha (HIF-1α) signaling pathway within cardiac tissues." (PMID 40508062, 2025). "Clinical studies have found that serum levels of hypoxia-inducible factor HIF-1α are significantly higher in patients with obstructive sleep apnea (OSA) who develop postoperative delirium (p < 0.01); elevated HIF-1α is an independent risk factor for PD (OR = 4.82)." (PMID 41332466, 2025). "A study of obstructive sleep apnea (OSA) in humans reported that the HIF1A protein level increase could damage the circadian clock." (PMID 35741857, 2022). "In addition, obstructive sleep apnea, results in chronic intermittent hypoxia and increased HIF-1α protein expression." (PMID 23050013, 2012). "As a particularity, HIF-1α levels are also increased in the brains and livers of patients with NAFLD and in those with obstructive sleep apnea, aggravating the progression of liver disease and chronic intermittent hypoxia." (PMID 35627959, 2022). "The obstructive sleep apnea (OSA) patients have less sleep and worse sleep quality, in which the serum hypoxia-inducible factor 1α (HIF-1α) protein level as a key factor of cellular oxygen metabolism is significantly higher." (PMID 34575915, 2021). "This suggests that STAT3 and HIF1A may play significant roles in obstructive sleep apnea development with no detectable protein expressions observed for other targets in adipose tissue." (PMID 40129771, 2025).